ACLY (ATP citrate lyase)
Description:
Catalyzes the cleavage of citrate into oxaloacetate and acetyl-CoA, the latter serving as common substrate in multiple biochemical reactions in protein, carbohydrate and lipid metabolism.
Synonyms: ACL; ATPCL; CLATP
Tractability: Small molecule: an approved drug acts on it; a structure with a bound ligand is known; a high-quality ligand is known; it has a high-quality binding pocket; it belongs to a druggable protein family. Antibody: its Gene Ontology location is reachable by antibodies, with high confidence. PROTAC: UniProt records ubiquitination sites on it; ubiquitination databases record sites on it; its protein half-life has been measured; a small molecule that binds it is known.
Target class: Enzyme; Transferase
Gene: Protein-coding gene on chromosome 17 (41,866,916 to 41,930,545, reverse strand). Ensembl gene ENSG00000131473.
Subcellular location: Cytoplasm, cytosol
Subcellular location (Human Protein Atlas): Cytosol; Basal body; Nucleoplasm; Primary cilium transition zone; Principal piece
Pathways (Reactome):
Metabolism: ChREBP activates metabolic gene expression; Fatty acyl-CoA biosynthesis
Immune System: Neutrophil degranulation
Gene Ontology:
Molecular function: ATP citrate synthase activity; protein binding; ATP binding; acyltransferase activity, acyl groups converted into alkyl on transfer; catalytic activity
Biological process: acetyl-CoA biosynthetic process; citrate metabolic process; coenzyme A metabolic process; fatty acid biosynthetic process; lipid biosynthetic process; negative regulation of ferroptosis; oxaloacetate metabolic process; cholesterol biosynthetic process; acyl-CoA biosynthetic process; acyl-CoA metabolic process; malonyl-CoA biosynthetic process
Cellular component: ATP-dependent citrate lyase complex; cytosol; extracellular exosome; membrane; azurophil granule lumen; extracellular region; ficolin-1-rich granule lumen
Genetic constraint (gnomAD): Loss-of-function variants: 39 observed, 127.05 expected, observed/expected ratio (o/e) 0.31, 90% interval 0.24 to 0.4. The upper end of that interval is the gene's LOEUF score, 0.4, which puts it in group 1 of 6, group 1 being the genes least tolerant of losing a copy. Missense variants: 1,007 observed, 1,451.3 expected, observed/expected ratio (o/e) 0.69, 90% interval 0.66 to 0.73. Synonymous variants: 482 observed, 554.53 expected, observed/expected ratio (o/e) 0.87, 90% interval 0.81 to 0.94.
Homologues: Orthologues: macaque ACLY (99% identical), pig ACLY (98% identical), dog ACLY (98% identical), mouse Acly (98% identical), rat Acly (98% identical), rabbit ACLY (97% identical), guinea pig ACLY (96% identical), chimpanzee ACLY (95% identical), tropical clawed frog acly (91% identical), zebrafish aclya (86% identical), zebrafish aclyb (83% identical), Drosophila melanogaster ATPCL (70% identical), and 2 more.
Diseases named in the same sentence as ACLY in open-access papers:
ACLY is named in the same sentence as 254 diseases in open-access papers, as found by Europe PMC text mining. Sharing a sentence is not in itself a finding about the gene and the disease. The quoted sentences say what the papers report.
breast cancer (59 papers, 1979 to 2025). A primary or metastatic malignant neoplasm involving the breast. "In the context of HER2-positive breast cancer, genes including ACLY, FASN, CPT1/2, CD36, and SCD1 have been associated with drug sensitivity to targeted therapies 34,35." (PMID 40303293, 2025). "ACLY is overexpressed in breast cancer and its presence has been suggested as a diagnostic marker for recurrence and possible chemotherapy resistance." (PMID 34298660, 2021). "We show here that loss of BRG1 attenuated FASN, ACC, and ACLY expression and impaired de novo lipid synthesis in breast cancer cells with a concomitant decrease in cell proliferation." (PMID 27223259, 2016). "ACLY has been identified in EVs associated with cancers of the breast and prostate." (PMID 40214422, 2025). "Phosphorylated ACLY expression was significantly associated with stage, differentiation and prognosis in patients with lung adenocarcinoma, and high ACLY expression was associated with drug resistance, recurrence and poor prognosis in breast cancer." (PMID 39881208, 2025). "Moreover, a decrease in lipid metabolism genes (e.g., Acly (ATP citrate lyase), Scd1, Acox1 (Acyl-CoA oxidase 1)) and an increase in cell cycle/DNA-damage-response genes (e.g., Brca1 (Breast Cancer 1), Bax (Bcl-2-associated X protein)) were observed." (PMID 39941720, 2025). "ACLY is reported to be up-regulated in many cancer cells such as glioblastoma, breast cancer, colorectal cancer, osteosarcoma, prostate cancer, cervical cancer and lung cancer, indicating overexpression of ACLY is a hallmark of cancer." (PMID 35646898, 2022). "ACLY overexpression has been associated with poor prognosis in breast cancer, and miR-22 by targeting ACLY, has been proposed as a potential biomarker of poor prognosis in breast cancer." (PMID 33050166, 2020). "Among the enzymes involved in lipid metabolism, ACLY has an advantage as an upstream therapeutic target, making it a preferred target for inhibiting lipid synthesis in breast cancer cells." (PMID 40002245, 2025). "mTORC2, on the other hand, phosphorylates ACLY at Ser455, enhancing its activity and promoting de novo fatty acid synthesis in breast cancer." (PMID 40002245, 2025). "In another study, overexpression of ACLY in breast cancer cells increased the expression of the snail protein, which ultimately induced tumorigenesis and cancer stemness." (PMID 40002245, 2025). "We found that IL4 induced the phosphorylation of AKT and ACLY in both human and murine mammary cancer cell lines." (PMID 38731867, 2024). "Conversely, inhibition of ACLY diminishes the invasiveness of breast cancer cells, while targeting ACLY reduces the proliferative potential and cisplatin resistance of ovarian cancer cells." (PMID 38994204, 2024). "Studies have shown that ACLY is abnormally expressed in breast cancer, prostate cancer, bladder cancer, lung cancer, gastric cancer, liver cancer and colon cancer." (PMID 38426936, 2024). "High expression of ACLY in breast cancer tissues is conversely proportional to disease stage and prognosis." (PMID 39834807, 2024). "The inhibition of cell death by co-treatment with an ACLY inhibitor has been observed in other breast cancer cell lines." (PMID 37899460, 2023). "Few studies have investigated the effect of ACLY inhibitors in influencing the effect of tamoxifen on breast cancer cells." (PMID 35448537, 2022). "This abrogation significantly suppressed their growth, highlighting the pivotal role of mTORC2-mediated phosphorylation of ACLY in breast cancer progression." (PMID 35448537, 2022). "In breast cancer, miR-22 inhibited the growth and metastasis by downregulating the expression of the proto-oncogene ATP citrate lyase (ACLY)." (PMID 35757325, 2022). "In this study, we found that ACLY enzymatic activity was increased in breast cancer-derived sEVs isolated from the MDA-MB-231 cell line, in comparison with sEVs isolated from MCF7 and MCF10A cell lines." (PMID 35203617, 2022).
breast cancer (continued). "Recent studies highlight ACLY as a potential biomarker for predicting breast cancer recurrence in patients." (PMID 35203617, 2022). "Oxidized ATM promotes breast cancer stem cell enrichment through facilitating the glycolytic flux to mitochondrial pyruvate and citrate and regulating ATP-citrate lyase (ACLY) activity, resulting in acetyl-CoA accumulation in the cytoplasm." (PMID 34638609, 2021). "Changes in ACLY expression have been found in diverse types of tumors including breast cancer, suggesting that this enzyme plays a crucial role in cancer metabolism." (PMID 33808259, 2021). "ACLY has been reported to have a strong expression in breast cancer tissue, with respect to adjacent normal tissues, and silencing ACLY expression in MCF-7 cell line suppressed cell viability and increased cell apoptosis." (PMID 33808259, 2021). "After β-catenin knockdown a decrease in expression of acetyl-CoA carboxylase, ATP-citrate lyase, and monoacyl glycerol lipase were all seen, suggesting a significant role in β-catenin function in breast cancer cells." (PMID 34298660, 2021). "Inhibition of ACLY by siRNAs or chemical inhibitors significantly impairs the growth of CSCs derived from human non-small cell lung carcinoma or breast cancer 64-66." (PMID 32641978, 2020). "ACLY plays a critical role in determining the histone acetylation, and ACLY knockdown leads to apoptosis and growth suppression in breast cancer cells." (PMID 31828117, 2019). "Low molecular weight cleaved form of cyclin E, a powerful independent predictor of survival in women with progressed breast cancer, was shown to interact with ACLY and promote aberrant lipid metabolism pathways in breast cancer tumorigenesis." (PMID 30717356, 2019). "Low molecular weight cyclin E upregulates ACLY enzymatic activity, subsequently promoting transformation, migration and invasion of breast cancer cells." (PMID 31511060, 2019). "There are studies in breast cancer, which suggest that depletion of ACLY suppressed breast tumor growth and progression." (PMID 30717356, 2019). "ACLY overexpression and activation increase metabolic activity in proliferating cells via activation of Akt signaling in glioblastoma, colorectal cancer, breast cancer, non-small cell lung cancer, and hepatocellular carcinoma etc.." (PMID 30717356, 2019). "Herein, we report the identification and characterization of Ser-455 in ATP citrate lyase (ACL) as a molecular target of dysregulated mTORC2 signaling pathway in HER2+/PIK3CAmut breast cancer cells." (PMID 27015560, 2016). "Although an extreme abnormal activation of this enzyme in breast carcinoma samples was described already 35 years ago, ACLY contribution to breast cancer development and progression is yet unclear clear and requires further investigation." (PMID 25643809, 2015). "In addition, inhibition of the SREBP1-dependent enzyme ACLY has been reported to enhance the efficacy of tamoxifen in breast cancer cells; ACLY additionally is a potential biomarker for predicting breast cancer recurrence." (PMID 40427160, 2025). "Furthermore, ACLY is implicated in the resistance to tamoxifen, palbociclib, and paclitaxel in breast cancer, whereas ACLY inhibition can re-establish sensitivity to these drugs and halts tumor progression." (PMID 39834807, 2024). "Our study showed that Chidamide could inhibit the highly expressed ACLY mRNA in breast cancer cells, therefore, it is speculated that ACLY could be a potential drug target for Chidamide in the treatment of breast cancer." (PMID 36425653, 2022). "To further dissect the potential relationship between ACLY expression and citrate level in tumor cells, we determined ACLY mRNA expression in different types of tumor cell lines, including breast cancer MCF7 and MDA‐MB‐231, colon cancer HCT116 and HT29, and lung cancer H1299 and A549 cell lines." (PMID 34747157, 2022). "ACLY knockdown significantly reduces the CSC population in breast cancer cells 62,66." (PMID 32641978, 2020).
breast cancer (continued). "Similarly, two enzymes catalyzing rate limiting steps upstream of FASN in de novo fatty acid synthesis, ACC and ACLY, are often dysregulated in cancer and have been proposed as breast cancer therapeutic targets." (PMID 27223259, 2016). "Similarly to SLC25A1, ACLY is significantly elevated in a variety of cancers, including melanoma, hepatocellular carcinoma, lung cancer, prostate cancer, and breast cancer." (PMID 39881208, 2025). "In the study of various tumors, including breast cancer, malignant mesothelioma, gastric cancer, salivary adenoid carcinoma, and noncoding RNA can affect the expression of lipid metabolism enzymes by directly binding to ACLY or by classical ceRNA mode, thus changing the malignant process of tumors." (PMID 36452489, 2022). "Analysis of the METABRIC database revealed that genes related to fatty acid metabolism, such as ACLY, CPT1A, FASN and SCD, are most highly expressed in HER2-positive breast cancer." (PMID 40303293, 2025). "Among ACLY inhibitors, hydroxycitric acid (HCA) and bempedoic acid (BA) have been investigated in breast cancer cell lines." (PMID 40002245, 2025). "For instance, silencing of ACLY by siRNA significantly decreased cell viability and increased apoptosis of MCF-7 breast cancer cells." (PMID 40214422, 2025). "Several studies have highlighted enzymes involved in de novo fatty acid biosynthesis, including ACLY, ACC, FASN, and SCD1, which are upregulated in breast cancer." (PMID 40002245, 2025). "In breast cancer, FA synthesis was reported to be heightened via the upregulation of several lipogenic enzymes, such as FASN and ACLY." (PMID 39351361, 2024). "ORL inhibits angiogenesis (VEGF, MMP-9, and CXCR4/CXCL12) and fatty acid synthesis (ACLY, ACC, and FASN) genes and protein expression with the induction of apoptotic genes in different breast cancer cell lines." (PMID 38256929, 2024). "Multiple studies have shown that ACLY is highly expressed in tumors, including gastric cancer 29, non-cellular lung cancer 30, breast cancer (BC) 31, and ovarian cancer 32, and is associated with poor prognosis." (PMID 37497413, 2023). "ATP citrate lyase (ACLY), an enzyme involved with de novo synthesis of cholesterol and FA, is overexpressed in breast cancer." (PMID 37046596, 2023). "For example, ACLY is involved in the AMPK pathway, which plays a key role in mediating chemoresistance in breast cancer." (PMID 36064336, 2022). "Our findings support further efforts to investigate these enzymes, especially ACLY, SIRT1, and SIRT6 for breast cancer diagnosis and therapy." (PMID 35203617, 2022). "Herein, taking into account that leptin induces SREBP‐1 in MCF‐7 breast cancer, we have identified SREBP‐1 target genes in response to leptin stimulation, including FASN, ACLY, and FADS2." (PMID 33226729, 2021). "Imbalzano and colleagues have demonstrated that BRG1 activates the transcription of several enzymes involved in fatty acid synthesis, including ATP citrate lyase (ACLY) and acetyl CoA carboxylase (ACC), to drive breast cancer proliferation." (PMID 33718362, 2021). "For instance, the lipogenic enzyme ATP-citrate lyase (ACLY) has been shown to interact with the low molecular weight isoform of cyclin E to promote the transformation, migration and invasion of breast cancer cells." (PMID 32509584, 2020). "For example, ATP citrate lyase (ACLY) is required for low molecular weight cyclin E (LMW-E)-mediated transformation, migration, and invasion in breast cancer cells." (PMID 31277295, 2019).
breast cancer (continued). "Our results here show that the elevated levels of lipid synthesis found in breast cancer are dependent on BRG1 acting to upregulate the transcription of FASN, ACC, ACLY and other genes involved in fatty acid synthesis." (PMID 27223259, 2016). "The upregulation of ATP citrate lyase (ACLY) increases the expression of the resistant proteins such as ABCB1/ABCG2, making breast cancer cells resistant to docetaxel, thereby suggesting ACLY as a potential predictive biomarker of tumor recurrence in breast cancer." (PMID 40843360, 2025). "ACLY levels are increased in CRC and other cancer types (breast cancer, hepatocellular carcinoma)." (PMID 36578540, 2022). "Moreover, SREBP as well as ATP Citrate Lyase (ACLY), a downstream target of SREBP, have been found to be upregulated in glioblastoma, colorectal cancer, breast cancer, non-small cell lung cancer, and hepatocellular carcinoma." (PMID 35198567, 2021). "In breast cancer, a high demand of FA from de novo synthesis has been reported as a response to the overexpression of several enzymes, such as fatty acid synthase (FASN), acetyl-CoA carboxylase (ACC) and ATP citrate lyase (ACLY)." (PMID 29438405, 2018). "ACLY expression is increased in metastatic breast cancer lines in comparison to non-tumorigenic and non-metastatic cell lines." (PMID 21049007, 2010). "Interestingly, inhibiting ACLY reduced the intracellular citrate level and cell viability of breast cancer cell lines more effectively than inhibiting citrate transport protein (CTP), but whether inhibiting both CTP and ACLY produces a synergistic antitumour effect is underexamined." (PMID 35448537, 2022).